GSK3B (glycogen synthase kinase 3 beta)
Diseases named in the same sentence as GSK3B in open-access papers (continued):
Sharing a sentence is not in itself a finding about the gene and the disease.
osteosarcoma (66 papers, 2009 to 2025). A usually aggressive malignant bone-forming mesenchymal neoplasm, predominantly affecting adolescents and young adults. "Research has indicated a significant association between the GSK3β/β-catenin signaling pathway and osteosarcoma proliferation." (PMID 38720781, 2024). "Accumulating evidence indicates that Akt/GSK-3β is linked to osteosarcoma progression and anti-chemotherapeutic drugs." (PMID 35112982, 2022). "Here, we set out to explore the underlying molecular mechanisms of GSK3β in the metastasis of osteosarcoma via small molecular inhibitors and siRNA knock down analysis." (PMID 33969873, 2021). "In the present study, we explored the therapeutic efficacy of GSK-3β inhibition against osteosarcoma and the underlying molecular mechanisms in an orthotopic mouse model." (PMID 27780915, 2016). "That same group has also reported the loss of Wnt/β-catenin pathway activity in osteosarcoma cells by measuring the nuclear β-catenin level, and using a GSK3β inhibitor." (PMID 23125530, 2012). "Additionally, the metastasis of osteosarcoma cells is associated with AKT-mediated GSK3β phosphorylation and ERK1/2 phosphorylation." (PMID 38612399, 2024). "In summary, our study revealed that inhibition of GSK-3β might suppress the osteosarcoma invasion and migration via the pathways associated with PTEN and phosphorylation of focal adhesion kinase, followed by reduced expression of MMP-2 or MMP-9." (PMID 33969873, 2021). "Moreover, to validate the anti-osteosarcoma effect is achieved specifically via cantharidin-caused Wnt/β-catenin signaling inactivation; we pretreated 143B cells using specific GSK-3β inhibitor (CHIR99021) before being challenged using 2.5 μM cantharidin." (PMID 34326690, 2021). "In contrast to an earlier study, the present results suggest that stabilization and activation of β-catenin may be a mechanism which underlies the efficacy of GSK-3β inhibition in osteosarcoma." (PMID 27780915, 2016). "It is of interest whether GSK-3β inhibition has therapeutic efficacy against osteosarcoma cells where increased β-catenin has been linked to malignancy." (PMID 27780915, 2016). "Therefore, inhibition of GSK-3β may provide indirect benefits for the treatment of osteosarcoma by limiting the extent of chemotherapy-associated bone marrow injury and by preserving tumor-adjacent stromal cells." (PMID 27780915, 2016). "The effect of GSK-3β inhibition was observed in the U2OS cells after knock-down of β-catenin expression, suggesting that β-catenin signaling-independent mechanism(s) such as alteration in NF-κB activity may underlie the efficacy of GSK-3β inhibition against U2OS osteosarcoma cells." (PMID 27780915, 2016). "Our findings reveal that troxerutin effectively inhibits CD155, attenuates the SRC/AKT/GSK3β signaling cascade, diminishes the nuclear localization of β-catenin, and consequently mitigates osteosarcoma stemness." (PMID 40217455, 2025). "SB216763 can induce apoptosis in human osteosarcoma cells by downregulating GSK-3β expression and significantly inhibits GSK-3β phosphorylation in serum-starved retinal neurons." (PMID 39936979, 2025). "Mechanistically, CGREF1 enhances Cyclin D expression by modulating GSK3β/β-catenin signaling within the Wnt pathway, thereby promoting the transition of osteosarcoma cells from G1/G0 to S phase and facilitating their proliferation." (PMID 39707194, 2024). "Our findings demonstrate that CGREF1 exerts regulatory control over the activation level of the Wnt pathway by modulating GSK3β/β-catenin signal transduction within this pathway, thereby influencing the malignant proliferative behavior of osteosarcoma cells." (PMID 39707194, 2024). "Collectively, these findings suggest that CGREF1 exerts an influence on Cyclin D expression through the regulation of GSK3β/β catenin signaling in the wnt pathway, thereby modulating the malignant proliferation of osteosarcoma cells." (PMID 39707194, 2024).
osteosarcoma (continued). "In conclusion, our results suggested that PIP improved the chemosensitivity of osteosarcoma cells to DOX by weakening the PI3K/AKT/GSK3β signaling pathway." (PMID 36895009, 2023). "Since controversial conclusions have been reported on the role of GSK-3β pathway in osteosarcoma, it is crucial to further investigate the role of GSK-3β in osteosarcoma for clinical therapeutic applications." (PMID 37108323, 2023). "We verified that PHLDA3 played a tumor suppressor role in osteosarcoma and suppressed cell proliferation, migration and enhanced cisplatin-induced cell apoptosis via regulating the Akt/ GSK-3β signaling pathway." (PMID 35112982, 2022). "Mechanistically, our data revealed that PHLDA3 negatively regulates the Akt/GSK3β signaling cascade in osteosarcoma." (PMID 35112982, 2022). "Our study aimed to investigate the roles of glycogen synthase kinase 3β (GSK3β) in human osteosarcoma metastasis." (PMID 33969873, 2021). "Other studies demonstrated that pharmacological inhibition or depletion of GSK3β by siRNA decreases osteosarcoma cell proliferation despite an increased nuclear translocation of β-catenin and expression of its target genes." (PMID 34062831, 2021). "More relevantly, pleiotrophin elevated chemoresistance to Adr in osteosarcoma cells by inducing the GSK3β/β-catenin signaling." (PMID 34516354, 2021). "In our study, the expression of GSK-3β in osteosarcoma tissues from patients with metastasis is higher than that without metastasis." (PMID 33969873, 2021). "For instance, activation of the PI3K/GSK-3b/b-catenin signaling promotes the progression and aggressiveness of osteosarcoma." (PMID 33901239, 2021). "In the osteosarcoma cell line MG-63, the inhibition of GSK3β with either AR-A014418 or SB216763 also reduced FAK activity, which is known to regulate invadopodia formation by sequestration of the invadopodia-inducing Src kinase at focal adhesions." (PMID 34440861, 2021). "The expressions of GSK3β, p-GSK3βSer9, and p-GSK3βTyr216 in human osteoblast cells (hFOB1.19) and human osteosarcoma cells (MG63, SaOS-2, and U2-OS) were detected by Western blotting." (PMID 33969873, 2021). "In our study, inhibition of GSK-3β with small-molecular GSK3β inhibitors significantly reduced the migration and invasion ability of osteosarcoma cells." (PMID 33969873, 2021). "Tumor-derived CXCL5 can promote human CRC metastasis by activating ERK/Elk-1/Snail and AKT/GSK3β/β-catenin pathway, accelerate osteosarcoma growth and can serve as a biomarker for non-small cell carcinoma, etc.." (PMID 33240582, 2020). "Human osteosarcoma patients who had higher levels of active GSK-3β and nuclear-localized NF-κB had a worse prognosis than those patients with lower levels of active GSK-3 and NF-κB in terms of patient survival periods." (PMID 32365809, 2020). "Intriguingly, NC attenuated epithelial to mesenchymal transition (EMT) via regulation of Akt and glycogen synthase kinase-3β (GSK-3β)/Snail, leading to suppression of migration and invasion in osteosarcoma cells." (PMID 33288736, 2020). "Epiafzelechin treatment decreased the activation of p-GSK-3β expression levels for the induction of apoptosis in osteosarcoma MG-63 cells." (PMID 32093300, 2020). "Apatinib can inhibit tumor cell growth by blocking the VEGFR2/STAT3/Bcl-2 or Akt/GSK3β/angiogenin signaling pathways, suppressing tumor angiogenesis in osteosarcoma and anaplastic thyroid cancer, respectively." (PMID 32509141, 2020). "So we conclude that URG4 can inactivate GSK-3β, thereby activating the β-catenin/cyclin D1 signaling pathway and promoting osteosarcoma cell proliferation." (PMID 32552851, 2020). "It was reported that the expression of Axin protein in GSK-3β was increased after baicalein treatment in MG-63 osteosarcoma cells." (PMID 32283909, 2020). "Recently, our group and others reported a therapeutic effect of GSK3β inhibition against osteosarcoma, rhabdomyosarcoma, synovial sarcoma and fibrosarcoma." (PMID 32503133, 2020).
osteosarcoma (continued). "Together, these results implicate the autocrine DKK1/GSK3β/β-catenin signaling in the regulation of osteoblast differentiation by osteosarcoma-derived Sema3A." (PMID 29720701, 2018). "We also investigated changes in expression, phosphorylation and co-transcriptional activity of β-catenin in osteosarcoma cells following GSK-3β inhibition." (PMID 27780915, 2016). "The TOP/FOP flash assay showed a significant increase in T-cell factor-dependent promoter activity in osteosarcoma cells following treatment with GSK-3β inhibitors, reflecting an increase in the co-transcriptional activity of β-catenin." (PMID 27780915, 2016). "A recent study showed that expression levels of GSK-3β, integrin β5 and focal-adhesion kinase in the primary tumors of osteosarcoma patients were significant predictors of poor response to neoadjuvant chemotherapy." (PMID 27780915, 2016). "GSK-3β inhibitors also induced the nuclear translocation of β-catenin in osteosarcoma cells, whereas the nuclear localization of β-catenin was constitutively observed in hFOB1.19 osteoblasts regardless of treatment with DMSO or GSK-3β inhibitor." (PMID 27780915, 2016). "An earlier study reported that GSK-3β promotes the survival and proliferation of osteosarcoma cells as well as their insensitivity to conventional chemotherapy, based on the known role for GSK-3β in positively regulating NF-κB-mediated signaling." (PMID 27780915, 2016). "Similar to other osteosarcoma cell lines, both GSK-3β inhibitors dose- and time-dependently suppressed U2OS cells survival." (PMID 27780915, 2016). "Inhibition of GSK-3β activity by pharmacological inhibitors or of its expression by RNA interference suppressed proliferation of osteosarcoma cells and induced apoptosis." (PMID 27780915, 2016). "In the present study, we explored the expression, activity and potential pathological role of GSK-3β in osteosarcoma, a rare but devastating disease that predominantly affects children and young adults." (PMID 27780915, 2016). "Together with an earlier study, our results confirm that osteosarcoma cells depend upon active GSK- 3β for their survival and proliferation, thus highlighting the potential benefit of targeting GSK-3β for the treatment of osteosarcoma." (PMID 27780915, 2016). "Our study thereby demonstrates a critical role for GSK-3β in sustaining survival and proliferation of osteosarcoma cells, and identifies this kinase as a potential therapeutic target against osteosarcoma." (PMID 27780915, 2016). "The influence of β-catenin expression on the therapeutic effects of GSK-3β inhibition of osteosarcoma cells was examined by RNA interference of β-catenin prior to the treatment of cells with GSK-3β inhibitor." (PMID 27780915, 2016). "Consistent with a previous study, these results indicate that both activity and expression of GSK-3β are necessary for osteosarcoma cell survival and proliferation, thereby suggesting a potential tumor-promoting role for this kinase in osteosarcomas." (PMID 27780915, 2016). "The small effect of GSK-3β inhibitors on hFOB1.19 cells and large effect on mice with orthotopic tumors further support the use of these agents for treatment of osteosarcoma in the clinical setting." (PMID 27780915, 2016). "The present experiment is proof-of-principle that GSK-3β inhibitors are active in a mouse models representing clinical osteosarcoma." (PMID 27780915, 2016). "Advanced molecular techniques, such as RNA sequencing and co-immunoprecipitation, have been instrumental in elucidating the mechanism of CD155 in activating the Wnt/β-catenin pathway via the SRC/AKT/GSK3β signaling axis, thereby enhancing the stem-cell-like properties of osteosarcoma cells." (PMID 40217455, 2025). "Moreover, the wnt reversion experiment further substantiated that CGREF1 modulated osteosarcoma cell proliferation through regulation of GSK3β/β-catenin signaling within the wnt pathway." (PMID 39707194, 2024).
osteosarcoma (continued). "Silencing or pharmacological inhibition of GSK3β in osteosarcoma cells leads to apoptosis." (PMID 39114307, 2024). "Furthermore, α-mangostin (10, 20, 30, 40, and 50 μM) demonstrated suppression of the Wnt/β-catenin pathway in osteosarcoma cells by reducing the protein levels of Wnt3a, phosphorylated glycogen synthase kinase 3 beta (GSK3β), and nuclear β-catenin." (PMID 39595559, 2024). "In addition, we found the upregulation of CD151 in the proteomic data, which is a known activator of GSK3B and positive regulator of β‐catenin expression, promoting osteosarcoma metastasis." (PMID 36520032, 2023). "Upon induction of senescence in a cancer line of mesenchymal origin (osteosarcoma, U2-OS), phosphorylation of NF-κB subunit p65 by GSK3β paves the way to a persistent SASP because it represses transcription of IκBα, which otherwise acts as the negative feedback loop restricting NF-κB activity." (PMID 35048158, 2022). "In osteosarcoma, nucleolin is involved in GSK3β-mediated stability of HIF1α mRNA." (PMID 36359210, 2022). "Moreover, the invasion ability of osteosarcoma cells following GSK3β knock-down by siRNA transfection for 72 h was obviously inhibited." (PMID 33969873, 2021). "Importantly, they demonstrated that the abnormal activation of GSK3β promoted the growth of osteosarcoma tumor." (PMID 33969873, 2021). "This suggests that cantharidin may be a prospective natural drug candidate for osteosarcoma treatment by targeting the miR-214-3p/DKK3/GSK-3β/β-catenin/LEF1 axis." (PMID 34326690, 2021). "Moreover, URG4 regulates cell cycle and proliferation in osteosarcoma through the GSK3β/β-catenin/cyclin D1 pathway." (PMID 32552851, 2020). "Additionally, Glycogen Synthase Kinase-3β (GSK-3β) is involved in cell cycle progression and proliferation of multiple tumors, including osteosarcoma." (PMID 32552851, 2020). "URG4, which is high-expressed in osteosarcoma, promotes cell cycle progression via GSK3β/β-catenin/cyclin D1 signaling pathway and may be a novel biomarker and potential target for the treatment of osteosarcoma." (PMID 32552851, 2020). "A recent study has found that GSK-3β inhibitors suppress proliferation in osteosarcoma cell lines and therefore might lead to normal osteogenesis." (PMID 31698687, 2019). "In addition, phosphorylated-Akt (Ser473) and phosphorylated-GSK3β (Ser9) obviously decreased in osteosarcoma cells treated with dioscin, which was followed by a reduction of β-catenin, especially nuclear β-catenin." (PMID 29497056, 2018). "Therefore, we further evaluated the effect of PPI on the activation of GSK-3β and β-catenin pathway in osteosarcoma cells." (PMID 28790389, 2017). "It is therefore important to address in future work whether GSK-3β inhibition can also modulate other chemotherapy drugs in osteosarcoma." (PMID 27780915, 2016). "This has led us to address whether GSK-3β could be a clinically-useful target for the treatment of osteosarcoma." (PMID 27780915, 2016). "The GSK-3β inhibitors significantly decreased the relative number of BrdU-positive proliferating osteosarcoma and osteoblast cells and increased the relative number of TUNEL-positive cells undergoing apoptosis in the osteosarcoma cell lines, but not in hFOB1.19 osteoblast cells." (PMID 27780915, 2016). "However, both pharmacological inhibition of GSK-3β and depletion of GSK-3β by siRNA inhibited proliferation of osteosarcoma cells, suggesting that the pharmacological doses used to inhibit GSK-3β were on target." (PMID 27780915, 2016). "For this, we tested the GSK-3β-specific siRNA on osteosarcoma cells." (PMID 27780915, 2016). "Expression and phosphorylation of GSK-3β in osteosarcoma and normal osteoblast cell lines was examined, together with efficacy of GSK-3β inhibition on cell survival, proliferation and apoptosis and on the growth of orthotopically-transplanted human osteosarcoma in nude mice." (PMID 27780915, 2016).
osteosarcoma (continued). "Since AKT inactivates GSK- 3β by phosphorylation of its S9 residue, we examined whether GSK-3β regulates AKT activity in osteosarcoma and osteoblast cells." (PMID 27780915, 2016). "Osteosarcoma and osteoblast cells showed similar basal levels of GSK-3β expression." (PMID 27780915, 2016). "In the present study, we demonstrated that knockdown of CGREF1 resulted in inhibition of GSK3β phosphorylation, reduction in β-catenin protein levels, and suppression of downstream Cyclin D activation by β-catenin, consequently leading to impaired proliferation ability of osteosarcoma cells." (PMID 39707194, 2024). "Thus, inhibition of GSK-3β may suppresses osteosarcoma cell migration and invasion by reducing the expressions of MMP-2 and MMP-9." (PMID 33969873, 2021). "Therefore, it could be speculated that GSK-3β might promote the osteosarcoma metastasis by reducing the stability of PTEN and increasing the phosphorylation of FAK, and then accelerate the secretions of MMP-2 and MMP-9." (PMID 33969873, 2021). "However, the miR-214-3p/DKK3/GSK-3β/β-catenin/LEF1 axis related pharmacological mechanism of cantharidin on osteosarcoma remains unknown." (PMID 34326690, 2021). "Interestingly, a previous study showed that cGKII activated C/EBPβ through phosphorylation of glycogen synthase kinase-3β (GSK-3β) in osteosarcoma cells, and our recent study showed that cGKII induced chondrocyte hypertrophic differentiation through the GSK-3β phosphorylation." (PMID 19229324, 2009). "For instance, research conducted by Zhiqiang Zhao and colleagues has demonstrated that DHM can inhibit the tumorigenesis of osteosarcoma by modulating the P38 (MAPK) and AMPKα/GSK3β/Sox2 signaling pathways." (PMID 40756986, 2025). "Recently, a study has shown that the expressions of ERK1/2, PARS40, and GSK3β are affected by CARM1, and the over‐expression of CARM1 promotes the proliferation of human osteosarcoma cells through the p‐GSK3β signaling pathway." (PMID 40611524, 2025). "For example the presence of pyruvate reduced SaOS-2 human osteosarcoma cell cytotoxicity to PAM by phosphorylation of ERK1/2, GSK3β, AMPK, and c-JUN and HSP60 dephosphorylation, which was primarily attributed to pyruvate scavenging H2O2." (PMID 38785562, 2024). "Through its ability to heighten the phosphorylation of GSK3β and activate the Wnt/β-catenin signaling pathway, CHMP4C plays a pivotal role in fostering the invasion and metastasis of osteosarcoma." (PMID 38720781, 2024). "The proliferation, invasion, and migration of osteosarcoma cells were significantly inhibited by knockdown of the expression of Lnc-CLSTN2-1:1, and the cell cycle-related signaling pathway PI3K/AKT/GSK-3β/cycinD1 was also inhibited." (PMID 38356713, 2024). "This study revealed for the first time that PIP can potentiate the sensitivity and cytotoxicity of DOX during osteosarcoma therapy in vitro and in vivo, which probably achieved by inhibiting the PI3K/AKT/GSK-3β signalling pathway." (PMID 36895009, 2023). "Our results showed that cantharidin up-regulated DKK3, decreased miR-214-3p, p-GSK-3β, active β-catenin, nuclear β-catenin and LEF1 expressions in osteosarcoma cells." (PMID 34326690, 2021). "Then the anti-osteosarcoma effects of cantharidin both in vivo and in vitro, as well as the specific contribution of miR-214-3p/DKK3/GSK-3β/β-catenin/LEF1 axis were further investigated." (PMID 34326690, 2021). "PPI induced inhibition of osteosarcoma cell viability was abolished upon addition of GSK-3β specific inhibitor, CHIR99021, while PPI induced inhibition of osteosarcoma cell viability and migration were potentiated by β-catenin silencing." (PMID 28790389, 2017). "Thus, inhibition of GSK-3β in osteosarcoma may potentially confer three therapeutic advantages: activation of the β-catenin-mediated pathway to inhibit tumor progression; attenuation of the activity of tumor-associated osteoclasts; and the enhancement of local bone preservation." (PMID 27780915, 2016).